LGR5 (leucine rich repeat containing G protein-coupled receptor 5)
Diseases named in the same sentence as LGR5 in open-access papers (continued):
Sharing a sentence is not in itself a finding about the gene and the disease.
gastric cancer (85 papers, 2012 to 2025). A primary or metastatic malignant neoplasm involving the stomach. "Increased LGR5 in human gastric cancer is associated with worse overall survival and a decreased tumor response grade following neoadjuvant chemotherapy." (PMID 36672658, 2023). "Recent studies have suggested a potential association between markers typically associated with gastric cancer stem cells, such as Lgr5 and Dclk1, and other cancer markers." (PMID 36937484, 2023). "Downstream LGR5 expression was upregulated in DAP3-deficient stomach cancer cells, while down-regulation of LGR5 re-sensitized DAP3-deficient stomach cancer cells to 5-FU and oxaliplatin." (PMID 38352299, 2023). "In our present study, we demonstrated that CAST is an oncogene associated with Lgr5 in gastric cancer via the WNT signaling pathway." (PMID 35625600, 2022). "Gastric cancer caused by PRMT5 loss exhibited the increase in Lgr5+ stem cells, which are proposed to contribute to both the gastric tumorigenesis and progression in mouse models." (PMID 35864961, 2022). "In other study of gastric cancer, high immunostaining scores for LGR5 were significantly associated with an increased risk of death." (PMID 33676447, 2021). "Collectively, NME2 was critical for the maintenance of stemness of gastric cancer stem-like cells via promoting the expression of stemness-associated transcriptional factors (c-Myc, LGR5, ALDH1, and Nanog) and anti-apoptosis genes (RIPK1, STARD5, and LIMS1)." (PMID 34628473, 2021). "Gastric cancer develops when cancer-associated genes are activated in Lgr5-positive stem cells and change them to CSCs." (PMID 31024835, 2019). "We chose a set of genes that were reported to encode gastric cancer stem cell markers such as LGR5, CD133, CD44, CD54, ABCG2 and MSI1, and then performed qPCR to detect their expression in both NANOGP8-transfected (SGC7901-NANOGP8) and mock cells (SGC7901-NC)." (PMID 29689047, 2018). "LGR5, identified as one of the biomarkers of gastric cancer stem cells, is associated with the carcinogenesis of gastric cancer." (PMID 28968998, 2017). "The result demonstrated that the over-expression of LGR5 in MGC803 cells significantly enhance gastric cancer cell migration (p<0.01), which indicates that LGR5 is associated with cell migration and invasiveness." (PMID 28033430, 2016). "Zheng and his colleagues reported that leucine-rich repeat-containing G protein-coupled receptor 5 (LGR5) levels were significantly elevated in gastric cancer tissues, thus serving as an early diagnostic biomarker." (PMID 26568964, 2015). "LGR5 + gastric cancer stem cell-like cells (GCSCs) were associated with cisplatin resistance." (PMID 39821694, 2025). "LGR5 expression is a hallmark not only of murine but also of human gastric cancers." (PMID 39191487, 2024). "The tendency for low LGR5 expression in EBV-positive tumors may be a feature of EBV-associated gastric cancer." (PMID 33676447, 2021). "High Lgr5 expression was also associated with gastric cancer angiogenesis." (PMID 28404940, 2017). "Recently, studies have demonstrated the expression of LGR5 in several tumors including colorectal, gastric carcinoma, esophageal adenocarcinoma, liver, ovarian carcinoma and Ewing sarcoma and have shown that the overexpression of LGR5 is associated with poor prognosis." (PMID 24172981, 2014). "In addition, studies of colorectal and gastric carcinoma, glioblastoma, and esophageal adenocarcinoma have all demonstrated heterogeneity of LGR5 expression and shown that high LGR5 levels are associated with worse outcomes." (PMID 23596566, 2013). "Interestingly, the trend has already begun; pilot report has shown that H. pylori infection is associated with increased DNA damage of Lgr5 positive cells in gastric cancer patients." (PMID 23217022, 2012). "Furthermore, the overall expression pattern of LGR5 in gastric cancer is compatible with the loss of control of the growth direction of neoplastic epithelia." (PMID 22530031, 2012).
gastric cancer (continued). "Therefore, it was speculated that targeting LGR5 could be a promising therapeutic strategy to improve chemoresistance in DAP3-deficient gastric cancer cells." (PMID 38352299, 2023). "Therefore, Lgr5 may provide a potential target for developing new therapies for gastric cancer, as well as a diagnostic marker for identifying CSCs in gastric cancer." (PMID 36937484, 2023). "Moreover, in 2017, in a study performed by Zhang and co-workers it was shown that in patients suffering from gastric cancer, the increase in Lgr5 markers caused by the disturbance in miR-132 expression resulted in more resistant to cisplatin during the treatment process." (PMID 33718760, 2021). "In this study, miR-132 (tumor progression marker) expression was enhanced in LGR5 + GCSCs and correlated with chemo-resistance in gastric cancer patients." (PMID 39821694, 2025). "LGR5 expression is upregulated in gastric cancer (GC) cells co-cultured with regulatory T cells (Tregs) or treated with exogenous TGF-β1." (PMID 41194856, 2025). "CAST is a potential cancer promoter in macrophage-infiltrated gastric cancer and regulates LGR5 expression." (PMID 41194856, 2025). "Lgr5+ cells are well-characterized stem cells in the gastrointestinal tract, and their role in gastric cancer is of particular interest as stem cell dysfunction is thought to be a key initiating event in human carcinogenesis." (PMID 40673273, 2025). "Core terms included LGR5, stem cells, Wnt pathway, cancer stem cells, gastric cancer, and intestinal stem cells." (PMID 41194856, 2025). "This evidence indicates that Lgr5+ chief cells are prone to malignant transformation and can serve as the cellular origin of gastric cancer." (PMID 41195276, 2025). "Several gastric cancer studies have indicated relationships between LGR5 expression and chemotherapy resistance." (PMID 39821694, 2025). "A gastric cancer study suggested that when the LGR5 + stem cell population is depleted, LGR5- cells move into the stem cell niche and are directed to revert to LGR5 + stem cells, thereby restoring tissue homeostasis." (PMID 39821694, 2025). "In gastric cancer, LGR5 expression shows spatial heterogeneity, and its high expression has been linked to increased proliferation and invasion, although some studies report context-dependent effects on patient outcomes." (PMID 41194856, 2025). "Pten and Smad4 ablation in Lgr5+ murine gastric stem cells was also independently shown to give rise to gastric cancer of the intestinal type." (PMID 39191487, 2024). "For example, the application of LGR5-targeting peptide probe enables the fluorescence rate of gastric cancer cells is 2 to 10 times higher than that of control cells." (PMID 38706913, 2024). "Given that Lgr5+ stem cells give rise to experimentally induced gastric cancer in vivo and are targeted by H. pylori both in vivo and in vitro, we asked how H. pylori would affect the biology of this lineage." (PMID 39191487, 2024). "It has been discovered that gene deletion in Lgr5+ stem cells leads to the formation of adenoma and invasive intestinal-type gastric cancer (GC) after three months, mainly in the antrum." (PMID 38672239, 2024). "For example, DTCs of gastric cancer express various stem cell markers, such as LGR5, TROY and ALDH1A1, and ALDH1A1 can promote the formation of DTC of acute myeloid leukemia cells through up-regulating mTOR." (PMID 37483492, 2023). "Lgr5 (Leucine-rich repeat-containing G protein-coupled receptor 5) is a transmembrane protein that is considered a marker for cancer stem cells (CSCs) in various types of cancer, including gastric cancer." (PMID 36937484, 2023). "LGR5 was demonstrated as an important downstream target of β-catenin signaling, and aberrant LGR5 expression reduced apoptosis in gastric cancer cells treated with 5-FU and oxaliplatin by suppressing caspase 3 cleavage." (PMID 38352299, 2023).
gastric cancer (continued). "It has been found that Lgr5+ cells can initiate and maintain tumors, and they are resistant to chemotherapy, making Lgr5 a promising therapeutic target for gastric cancer treatment." (PMID 36937484, 2023). "Immunohistochemistry was used to detect the expression of FAP, CD10, and GPR77 in CAFs; the EMT markers (N-cadherin, Snail1, and Twist1) and the CSC markers (ALDH1, CD44, and LGR5) in gastric cancer cells." (PMID 37277751, 2023). "When deleting both PTEN and Smad4 in the gastric antral Lgr5+ stem cells, we observed the invasive intestinal-type gastric cancer in double mutant mice within as early as 3 months post induction." (PMID 35864961, 2022). "Amplification of β-catenin has been reported in gastric cancer coinciding with enhanced nuclear β-catenin localization, and Lgr5+ chief cells were identified as a key cell of origin in early gastric cancer." (PMID 35260534, 2022). "Consistent with the notion that Lgr5 is the target of Wnt/β-catenin signaling, whose activation is the most predominant driver for gastric tumorigenesis, Prmt5 mutant gastric cancer showed the activation of Wnt/β-Catenin signaling." (PMID 35864961, 2022). "Our and other groups have demonstrated that mutant Lgr5+ cells can initiate gastric cancer and accelerate the progression and metastasis of gastric cancer 5, 33-35." (PMID 35864961, 2022). "Ectopic AKAP8L in gastric cancer cells and spheroids elevated the expression of stem cell markers, including Lgr5, CD133, CD44, Oct4, Sox2, as determined by qPCR, Western blot analysis." (PMID 36522343, 2022). "The MKN45 cells with GRP78 knockdown exhibited decreased formation of colonies and spheroids and decreased expression of gastric cancer stem cell–like markers (LGR5, CD24, CD44, and ALDH1) and stemness-related transcriptional factors (SOX2 and Nanog)." (PMID 35740372, 2022). "We found that IL-17RB expression was significantly upregulated in spheroid cells and Lgr5-positive cells from the same tumor tissues of patients with gastric cancer (GC), which was closely correlated with the degree of cancer cell differentiation." (PMID 33649532, 2021). "For example, since LGR5 is a marker related to normal stem cells in gastric tissue and GCSCs, new therapies have been developed for eliminate LGR5+ cells in gastric cancer." (PMID 34503571, 2021). "Leucine-rich repeat-containing G-protein-coupled receptor 5 (LGR5) is an important cancer stem cell marker in gastric cancer." (PMID 33676447, 2021). "Two stem cell populations have been identified in gastric cancers: slow cycling cells expressing the transcription factor Mist1 in the gastric corpus and Leucine-rich repeat-containing G-protein coupled receptor 5 (Lgr5)-expressing cells in the gastric antrum." (PMID 32849491, 2020). "The aim of this study was to examine the role of Lgr5 in the microenvironment of gastric cancer (GC), and to explore possible immunological mechanisms influencing Lgr5 expression that are governed by regulatory T cells." (PMID 31417548, 2019). "Tumor and paired adjacent tissues of intestinal-type gastric cancer (GC) patients (n = 30) were evaluated for LGR5 and TROY expression by immunohistochemistry." (PMID 30501144, 2019). "While antral stem cells expressing Lgr5, Mist1 or Sox2 may be among the gastric cancer origin cells in the setting of Apc loss, Lgr5+ cells have been implicated in more invasive types of gastric cancer, characterized by the simultaneous loss of Pten and Smad4, or by the loss of Lats1 and Lats2." (PMID 30384487, 2018). "Because NANOGP8 promotes LGR5 expression the most significantly, and LGR5 is reported to be gastric cancer stem cell marker and one of the Wnt receptors, therefore, we want to explore if NANOGP8 can enhance Wnt signal transduction." (PMID 29689047, 2018). "Here, we aim to find the role of LGR5 in tumor cell proliferation and metastasis in gastric cancers." (PMID 30089773, 2018).
gastric cancer (continued). "Nevertheless, our results provide the first evidence that overexpression of LGR5 and activation of Wnt signaling pathway are potential biomarker for gastric cancer diagnostics and therapeutic targets for gastric cancer treatment." (PMID 30089773, 2018). "The positive rate of Lgr5 expression was 54.1% (172/318) in gastric cancer, which was much higher than that in the normal mucosal tissues (18.8%, 15/80, P=0.001)." (PMID 28404940, 2017). "Downregulation of Lgr5 expression in gastric cancer cells by the siRNA approach would result in a partial reduction in tumor angiogenesis." (PMID 28404940, 2017). "Both CD24 and LGR5 are gastric cancer stem cell biomarkers expressed simultaneously in gastric cancer tissues, whereas Ki67 is involved in the formation of gastric adenocarcinoma." (PMID 28968998, 2017). "Leucine-rich repeat-containing G protein-coupled receptor 5 (Lgr5) is a novel gastric cancer marker." (PMID 28404940, 2017). "It is very likely that, due to the accumulation of mutations, H. pylori infection, epigenetic changes, and genetic alteration, dysregulation of the signaling pathways that control these Lgr5+ stem cells will give rise to gastric cancer." (PMID 28230774, 2017). "The results indicated that Lgr5 expression was upregulated in gastric cancer and positively correlated with VEGF (r=0.305, P=0.001) and MVD (r=0.312, P=0.001)." (PMID 28404940, 2017). "Given its antagonistic relationship with leucine-rich repeat-containing G-protein-coupled receptor 5 (Lgr5), one of the gastric cancer stem cell markers, investigation of the potential role of RNF43 in gastric stem cancer cells is necessary." (PMID 28446252, 2017). "In the present study, we investigated Lgr5 expression in a large sample of gastric cancer tissues, and for the first time showed that Lgr5 expression was significantly and positively correlated with VEGF expression and MVD." (PMID 28404940, 2017). "The fact that PRRX1 promotes EMT through the Wnt/β-catenin pathway in gastric cancer and that LGR5 is a co-receptor of the Wnt/β-catenin pathway involved in tumorigenesis clearly suggests an intimate association between PRRX1, LGR5 and EMT." (PMID 28033430, 2016). "We characterized LGR5 and its association with 5 putative CSC markers, 4 stemness regulators, and 3 EMT inducers in three cell sources, i.e., gastric cancer tissues, gastric cancer cell lines and sphere cells." (PMID 28033430, 2016). "Here we report a novel, highly-penetrant mouse model of invasive gastric cancer arising from deregulated Hedgehog/Gli2 signaling targeted to Lgr5-expressing stem cells in adult stomach." (PMID 26859571, 2016). "Since the qPCR analysis of gastric cancer tissues only detected up-regulated expression of LGR5, CD44 and PRRX1 among the putative CSC markers, stemness regulators and EMT inducers, we next tried to use GC cell lines in vitro to confirm this result." (PMID 28033430, 2016). "The result showed that the over-expression of LGR5 in MGC803 cells promotes gastric cancer cell proliferation significantly (p<0.01)." (PMID 28033430, 2016). "To characterize the role of IL-17B/IL-17RB signaling on the stemness of gastric cancer, we performed real-time quantitative PCR to examine the expression of Oct4, Nanog, Lgr5, and Sall4 mRNA in MGC-803 cells treated with exogenous rIL-17B." (PMID 27146881, 2016). "Accumulating evidence in human cancer cell lines has now confirmed that LGR5 promotes the growth and survival of ovarian carcinoma, basal cell carcinoma, colorectal and gastric carcinoma, esophageal adenocarcinoma and liver carcinoma." (PMID 24172981, 2014). "In gastric cancer, LGR5+ cells were present at the luminal surface, in the tumour centre (between luminal surface and invasion front) and at the invasion front." (PMID 22530031, 2012).
gastric cancer (continued). "To further explore the significance of LGR5 for gastric cancer, we correlated the expression of LGR5 in intestinal type gastric cancer with various clinico-pathological patient characteristics." (PMID 22530031, 2012). "We systematically explored the histoanatomical distribution of LGR5+ cells in 100 patients with intestinal type gastric cancer." (PMID 22530031, 2012). "Most surprisingly, a very strong expression of LGR5 was found at the luminal surface of gastric cancer with decreasing staining intensities of the adjacent abluminal cells." (PMID 22530031, 2012). "In support of this contention, the expression of LGR5 in intestinal type gastric cancer correlated with the local tumour growth, nodal spread (as an indicator for the ability of colony formation) and patient survival." (PMID 22530031, 2012). "The clinico-pathological significance of LGR5 expression was studied in 100 patients with gastric carcinoma (GC)." (PMID 22530031, 2012). "Furthermore, upon tamoxifen-induced Kras (G12D) mutation (Lgr5-2A-CreER-T2tg/tg/LSL-Kras(G12D)tg/+), these cells directly progressed to gastric cancer." (PMID 41195276, 2025). "Another gastric cancer study found that LGR5-KD could re-sensitize DAP3-depleted gastric cancer cells to 5-fluorouracil (5-FU) and oxaliplatin." (PMID 39821694, 2025). "Lgr5+ cells are well-characterized intestinal stem cells, and their presence in the gastric antrum makes this model particularly relevant for studying antral-predominant gastric cancers." (PMID 40673273, 2025). "Furthermore, knockdown of LGR5 by small interfering RNA (siRNA) can inhibit angiogenesis in gastric cancer." (PMID 40210723, 2025). "Elevated Lgr5 expression, especially in conjunction with other early gastric cancer markers such as CD44 and CD133, has been postulated to be predictive of a particularly high risk of progression to an advanced stage of disease, i.e., low-grade dysplasia or later." (PMID 39191487, 2024). "Studies have shown that Lgr5 is overexpressed in gastric cancer and may play a role in the development and progression of the disease." (PMID 36937484, 2023). "Moreover, the decreased expression of LGR5 and β-catenin were observed in human gastric cancer by silencing Rspo2." (PMID 37946278, 2023). "For example, studies have shown that Lgr5 is overexpressed in gastric cancer and may play a role in the development and progression of the disease." (PMID 36937484, 2023). "Notably, overexpression of LGR5 has been observed in clinical gastric carcinoma, indicating its potential involvement in G.C. development." (PMID 38136437, 2023). "However, AQP5 can clearly distinguish these cell populations, suggesting that AQP5 is a more suitable target for the treatment of gastric cancer than LGR5." (PMID 36372898, 2022). "AQP5 and LGR5 were colocalized in gastric cancer tissue cells." (PMID 36372898, 2022). "Of note, GFP-expressing Lgr5+ cells were also observed in the invasive regions of gastric cancer." (PMID 35864961, 2022). "Furthermore, our study creates a link between AQP5 and LGR5 and highlights the necessity of targeting both surface markers simultaneously as a promising approach for the treatment of gastric cancer patients." (PMID 36372898, 2022). "Consistently, previous studies reported that regulatory T-cells (Tregs) promote LGR5 upregulation in gastric cancer cells through TGFβ1 signaling, with a likely involvement of Wnt signaling; Meanwhile, high LGR5 levels upregulated by TGFβ1 was thought to deteriorate gastric cancer patient prognosis." (PMID 33767593, 2021). "Several reports have investigated LGR5 expression in gastric cancer." (PMID 33676447, 2021). "In addition, Choi and colleagues have studied the relationship between this gene and the LGR5 gene in gastric cancer cells." (PMID 33718760, 2021). "Additionally, leucine-rich repeat-containing G-protein-coupled receptor 5 (LGR5) was identified as a robust CSC marker in murine gastric cancer." (PMID 33676447, 2021).